RIPK1 (receptor interacting serine/threonine kinase 1)
Diseases named in the same sentence as RIPK1 in open-access papers (continued):
Sharing a sentence is not in itself a finding about the gene and the disease.
COVID-19 (continued). "Our results suggest that SARS-CoV-2 may have an unexpected and unusual ability to hijack the RIPK1-mediated host defense response to promote its own propagation and that inhibition of RIPK1 may provide a therapeutic option for the treatment of COVID-19." (PMID 34663909, 2021). "Since RIPK1 is considered a master regulator of proinflammatory cell death, selectively targeting its kinase activity was hypothesised to mitigate the devastating sequelae of the hyperinflammatory state observed in late-stage severe COVID-19." (PMID 38419035, 2024). "Whether RIPK1 inhibition can emerge as an effective therapeutic strategy, either alone or in combination with other immunomodulatory therapies, in patients with severe COVID-19 warrants further investigation." (PMID 38419035, 2024). "Thus, SARS-CoV-2 may be able to hijack the RIPK1-mediated host defense response to its advantage and that inhibition of RIPK1 may provide a therapeutic option for the treatment of severe COVID-19 to help ending this public health emergency." (PMID 36969188, 2023). "In addition, there is a clinical trial using RIPK1 inhibitors for COVID-19 infected patients." (PMID 37090690, 2023). "Clinical trials of the immunomodulatory and clinical effects of another RIPK1 inhibitor, SAR443122, in patients with severe COVID-19 are currently in progress." (PMID 35912110, 2022). "Particularly interesting is Ripk1, a kinase activated by SARS-CoV-2 infection in lungs that when inhibited reduces the viral load and mortality in COVID-19 humanized mouse model." (PMID 36466830, 2022). "The protein levels of RIPK1, RIPK3, and MLKL are also elevated in the plasma of both moderate and severe COVID-19 patients." (PMID 39872161, 2022). "used the lung pathological samples of COVID-19 patients and cultured human lung organoids and ACE2 transgenic mice infected by SARS-CoV-2 to explore the role of RIPK1 in SARS-CoV-2 infection." (PMID 35655782, 2022). "Furthermore, our immunohistochemical analyses of pharyngeal epithelial cell samples from COVID-19 patients suggest that RIPK1 activation, and by implication, RIPK1-induced inflammatory cell death (ICD) may contribute to the course of SARS-CoV-2-induced infection." (PMID 33273695, 2021). "Since inhibition of RIPK1 can reduce the replication of both 323P and 323L SARS-CoV-2 in human lung organoids, our results suggest that RIPK1 kinase inhibitors may provide an effective therapy for severe COVID-19 as well as reducing the spread of SARS-CoV-2 variants." (PMID 34663909, 2021). "The absence of phosphorylation of RIPK1 or RIPK3 in the P21 infected mice provides additional evidence that SARS-CoV-2 does not induce necroptosis in the context of severe COVID-19." (PMID 38286985, 2024). "As the vast majority of these data are correlative, based solely on in vitro findings or obtained using non-SARS-CoV-2 models, the exact role of necroptotic cell death vs. inflammatory signaling evoked by RIPK1 and/or RIPK3 remains to be established in COVID-19." (PMID 35244141, 2022). "As RNA viruses can promote the inflammasome activation via RIPK1/RIPK3, Nec-1 may help in regulating this process by limiting inflammation and cytokines release induced by COVID-19." (PMID 34201847, 2021). "In recent years, proteomic studies and interactome analysis have identified many novel therapeutic targets and drug candidates for SARS-CoV-2; however, some of which have not been validated in COVID-19, such as receptor-interacting protein kinase 1 (RIPK1) targeted by ponatinib, an antitumor drug." (PMID 36182930, 2022). "As multiple RIPK1 inhibitors (Nec-1s, GSK′481/GSK′772, etc.)have been advanced beyond Phase I safety studies in human clinical trials, the authors suggested that the RIPK1 kinase inhibitors may provide effective therapy for severe COVID-19." (PMID 35655782, 2022).
Immunodeficiency (26 papers, 2016 to 2025). Failure of the immune system to protect the body adequately from infection, due to the absence or insufficiency of some component process or substance. "It is possible that the loss of function of the death domain of RIPK1 results in a combined immunodeficiency attributed to altered cytokine levels and necroptotic markers such as, IL-1β, IFIT1/3, CXCL1." (PMID 41019071, 2025). "The majority of pathogenic RIPK1 mutations are linked to a specific form of immunodeficiency termed Immunodeficiency 57 (IMD57)." (PMID 40007541, 2025). "Despite the deficit in these pro-inflammatory cytokines, there is a severe inflammatory component to RIPK1-deficiency immunodeficiency with autoinflammation, thought to be a function of enhanced activation of inflammasomes and over-production of IL-1β." (PMID 39762600, 2025). "Complete loss of RIPK1 in humans resulted in immunodeficiency and diarrhea; however, missense mutations within the death domain of RIPK1 impacting kinase activity resulted in IBD-like conditions." (PMID 41019071, 2025). "Biallelic loss of function (LOF) mutations in RIPK1 cause severe immunodeficiency in humans, characterised by impaired T- and B-lymphocyte differentiation, lymphocytopenia and diminished production of interleukin (IL)−6, tumour necrosis factor (TNF) and IL-12." (PMID 39762600, 2025). "Impairments of the scaffolding and kinase-specific functions of RIPK1, implicated in the pathogenesis of conditions which are characterised by severe immune dysfunction associated with cytokine dysregulation, have recently been reviewed." (PMID 39762600, 2025). "Previous research has demonstrated the vital role of RIPK1 in maintaining immune homeostasis 12, and there have been reports of patients with RIPK1-associated immunodeficiency or autoinflammatory diseases 13-16." (PMID 38164277, 2024). "The deletion mutation of RIPK1 gene can lead to severe immune deficiency and other diseases, while another missense mutation of RIPK1 gene can lead to inflammatory diseases." (PMID 36034412, 2022). "Unlike postnatal lethality of Ripk1 constitutive knockout mice, patients with RIPK1 biallelic LoF mutations were born alive, however, they suffered from severe and potentially lethal immunodeficiency, and one of them had autoinflammatory manifestations." (PMID 34163478, 2021). "From 2018 till now, six independent groups have reported patients with RIPK1-associated immunodeficiency or autoinflammatory diseases." (PMID 34163478, 2021). "Recently, four patients with severe immunodeficiency, gut inflammation, and progressive polyarthritis were identified with RIPK1 homozygous loss of function alleles." (PMID 30766537, 2019). "Additionally, mutations in SERPINB6 and RIPK1 are associated with autosomal recessive (ar) deafness (#613453) and immunodeficiency (#618108), respectively." (PMID 39360045, 2024). "RIPK1 deficiency caused by rare homozygous mutations could result in severe immunodeficiency, arthritis, and intestinal inflammation in human patients." (PMID 31519887, 2019). "Consequently, therapeutic interventions targeting RIPK1 might hold substantial promise in ameliorating associated immunodeficiencies." (PMID 40007541, 2025). "In addition, in human patients with inherited RIPK1 deficiency, defective differentiation of hematopoietic progenitors in the bone marrow could result in immune dysfunctions and/or system inflammation." (PMID 34840579, 2021). "RIPK1 deficiency has previously been reported in few patients presented with VEO-IBD, recurrent infections, combined immunodeficiency or autoinflammation syndrome." (PMID 38676845, 2024). "Hematopoietic stem cell transplantation restored not only immunodeficiency but also intestinal inflammatory pathology, indicating that RIPK1 in hematopoietic cells is critical to maintain intestinal immune homeostasis." (PMID 34462571, 2022).
Immunodeficiency (continued). "Remarkable insights on the RIPK1 function in human immune diseases have been revealed during the past few years and are summarized in the following section." (PMID 34163478, 2021). "The receptor-interacting protein RIPK1 (also called RIP1) mediates programmed necroptosis and apoptosis, and homozygous loss of function of the corresponding gene results in perinatal lethality and immune system disease." (PMID 39596040, 2024). "Although the mechanism of inflammation in humans, like mice, is due to increased cell death via necroptosis, the absence of immunodeficiency in Ripk1−/− mice and the viability of null alleles in humans, hints at a unique role for necroptosis specific to human immune cells." (PMID 30766537, 2019). "Notably, mice lacking RIPK1 experience acute perinatal lethality, succumbing to systemic inflammation and aberrant cell death, whereas humans with biallelic RIPK1 deficiency are viable, although they experience immunodeficiencies and autoinflammatory disease." (PMID 39186805, 2024). "Given RIPK1’s functions in regulating both immunological and epithelial responses, performing HSCT to treat these sufferers should be taken with caution since it may improve immunodeficiency." (PMID 38676845, 2024). "Given RIPK1’s roles in governing both immune and epithelial responses, using HSCT to cure these patients should be carefully considered, as it might ameliorate the immunodeficiency phenotype but not intestinal inflammation." (PMID 36466854, 2022).
glioblastoma (25 papers, 2014 to 2025). The most malignant astrocytic tumor (WHO grade IV). "For example, RIPK1 expression is significantly elevated in glioblastoma (GBM), which is also associated with poor prognosis of glioblastoma." (PMID 38652105, 2024). "Transcriptomic studies were carried out using USC Xena and R, while in vitro assays were performed with the glioblastoma human cell line U251 and the commercial RIPK1 inhibitor GSK2982772." (PMID 40565018, 2025). "With the aim of further studying the role of RIPK1 in the pathogenesis of DG, pre-clinical in vitro assays were performed using the human glioblastoma cell line U251 and the highly selective commercial RIPK1 inhibitor, GSK2982772." (PMID 40565018, 2025). "Overexpression of RIPK1 has also been observed in glioblastomas and is strongly correlated with poor prognosis." (PMID 41334873, 2025). "According to the tumor-promoting role of RIPK1 in glioblastoma, a recent study suggests the oncogenic function of RIPK1 in the lung epithelial cells that have acquired genetic mutations and epigenetic modifications caused by carcinogens." (PMID 33567618, 2021). "RIPK1 protein expression seems to be higher in glioblastoma grade IV, the most common adult malignant brain tumor, compared to lower grade glioma (I–III)." (PMID 33567618, 2021). "In general, RIPK1 maintains normal expression levels in many cancer types but in glioblastoma or lung cancer its expression has been found to be upregulated, affecting cancer prognosis negatively." (PMID 33567618, 2021). "For example, in glioblastoma, RIPK1 is commonly overexpressed, and the upregulation of RIPK1 expression is correlated with a poorer prognosis." (PMID 31122251, 2019). "Functionally, RIPK1 promotes glioblastoma cell proliferation, migration, and invasion." (PMID 41429922, 2025). "In addition, EGFRvIII is known to activate the NF-κB signalling pathway via RIPK1-ubiquitination, while WT EGFR seems to suppress this process leading to RIPK1-dependent apoptosis in glioblastoma." (PMID 38789573, 2024). "On the other hand, there is also evidence that necroptosis may promote carcinogenesis by inducing adaptive immunosuppression; for instance, RIPK1 is overexpressed in glioblastoma, lung cancer, and pancreatic ductal adenocarcinoma (PDAC), and RIPK3 and MLKL are highly expressed in PDAC." (PMID 35769473, 2022). "In order to study the relationship between RIPK1 expression levels and the aggressivity of diffuse gliomas, the TCGA-LGGGBM (The Cancer Genome Atlas-Low-Grade Glioma and Glioblastoma Multiforme) database was employed to evaluate 670 samples from patients." (PMID 40565018, 2025). "In U251 glioblastoma cells, CRISPR-Cas9-mediated ablation of RIPK1 or MLKL impaired cellular growth, as demonstrated by CCK-8 and colony-formation assays." (PMID 41429922, 2025). "For instance, RIPK1 expression in glioblastoma (GBM) has been correlated with a poorer prognosis." (PMID 34490126, 2021). "The expression of RIPK1 is generally maintained at a normal level in a variety of cancers, but its expression is upregulated in glioblastoma, lung cancer, and MDS, which has a negative impact on cancer prognosis." (PMID 34977874, 2021). "This suggests that mainly secondary necrosis and no RIPK1-dependent necroptosis was induced in the examined glioblastoma cell lines." (PMID 24678590, 2014). "Of note is that the observed necrosis is not RIPK1-dependent necroptosis, since glioblastoma cell death induced by RT and/or CT was inhibitable by zVAD-fmk, but not by necrostatin-1 (not shown)." (PMID 24678590, 2014).
glioblastoma (continued). "The RIPK1-dependent necroptosis inhibitors necrostatin-1 (Nec-1) and Nec-1s as well as siRNA-mediated silencing of RIPK3 inhibited edelfosine-induced necroptosis, resulting in increased caspase-dependent apoptosis in edelfosine-treated glioblastoma U118 cells." (PMID 25593994, 2014).
atherosclerosis (23 papers, 2018 to 2025). A disease characterized by the build-up of fatty material and calcium deposition in the arterial wall resulting in partial or complete occlusion of the arterial lumen. "In the present study, RIPK1S25D/S25D mice containing an S > D mutation in the kinase domain of RIPK1 were crossbred with ApoE−/− mice to investigate the role of RIPK1 kinase activity in experimental atherosclerosis." (PMID 35625752, 2022). "Recent research also reveals that RIPK1 in endothelial cells modulates protein synthesis pathways affecting NO-related signaling, and RIPK1 deficiency exacerbates vascular stenosis in transplant-associated atherosclerosis." (PMID 41562048, 2025). "Importantly, atherosclerosis was exacerbated in ApoE−/− mice carrying the RIPK1S25D/S25D mutation as compared to ApoE−/− RIPK1+/+ controls." (PMID 35625752, 2022). "Cumulatively, the data suggest that RIPK1 is emerging as a master switch that controls inflammation and cell survival in atherosclerosis progression, and phosphorylation of RIPK1, RIPK3 and MLKL are definitive indicators of necroptosis activation." (PMID 37863894, 2023). "A couple of studies discover that RIPK1 is abundant in early lesions of atherosclerosis in humans and mice." (PMID 35498045, 2022). "Together, these studies stress the complex involvement of RIPK1 either as a pro-survival scaffold or as an active kinase in atherosclerosis, which is even further complicated depending on the stage of plaque development." (PMID 35625752, 2022). "The expression of RIPK1 is also increased in early-stage atherosclerotic lesions of both human atherosclerosis patients and ApoE−/− mice." (PMID 39872161, 2022). "Inhibition of necroptosis in ApoE−/− mice with established atherosclerosis by RIPK1 inhibitor reduces atherosclerotic lesion size and markers of plaque instability." (PMID 39872161, 2022). "Long-term administration (4-week) of RIPK1 inhibitor accelerates atherosclerosis with increased lesion area in the plaques and more lipid accumulation in macrophages." (PMID 35498045, 2022). "Levels of RIPK3 as well as RIPK1 are elevated in human tissues affected by various pathological conditions, including ischemic stroke, atherosclerosis, and aortic aneurysm." (PMID 34867386, 2021). "By contrast, in a recent study, loss of MLKL, a downstream molecule of RIPK1/RIPK3 mediated necroptosis pathway, increased macrophage lipid accumulation in atherosclerosis." (PMID 34760938, 2021). "RIPK1 was identified as a central driver of inflammation in atherosclerosis by its ability to activate the NF-κB pathway and promote inflammatory cytokine release in mice (Mus musculus)." (PMID 33882827, 2021). "It is critical to identify an optimal therapeutic duration for potential clinical use of RIPK1 inhibitor in atherosclerosis or other related disease indications." (PMID 34760938, 2021). "Necroptotic cell death found in the necrotic core within atherosclerotic lesions provides the possibility of RIPK1/RIPK3-mediate necroptosis signaling pathway investigation in atherosclerosis." (PMID 34867386, 2021). "Here, we report that GSK547 (RIPK1i), a mono-selective kinase inhibitor that robustly targets RIPK1 in vivo plays a dual role in lipid metabolism and inflammation, conferring a stage-dependent impact on atherosclerosis." (PMID 34760938, 2021). "Here, we report that RIPK1 inhibition protected against early atherosclerosis, confirming a recent observation, however, surprisingly, it promoted atherogenesis in late stage." (PMID 34760938, 2021). "Taking advantage of ApoESA/SA mice, a new model combining both hypercholesterolemia and hypertension that rapidly develops atherosclerosis (manuscript under submission), we examined the impact of RIPK1 inhibition on advanced atherosclerosis." (PMID 34760938, 2021).